VGF (VGF nerve growth factor inducible)
Diseases named in the same sentence as VGF in open-access papers (continued):
Sharing a sentence is not in itself a finding about the gene and the disease.
Obesity (11 papers, 2009 to 2023). Accumulation of substantial excess body fat. "We conclude that some of the already identified variants in VGF from human polymorphism studies may contribute to eating disorders and obesity." (PMID 27088090, 2016). "Notably, the TLQP-21 derivative of VGF gene has been linked with the prevention of obesity in diet-induced mice." (PMID 27088090, 2016). "VGF ablation blocks obesity, hyperglycemia and hyperinsulinemia in MC4R-deficient mice, so this protein may function in these outflow pathways to regulate sympathetic nervous system activity and lipid storage." (PMID 19863797, 2009). "We felt that this was important, as the VGF gene itself was found to be significant in a study related to sleep and brain development, but the available literature linked VGF with homeostatic processes, insulin secretion, and other metabolic functions that could be associated with obesity." (PMID 27088090, 2016). "VGF, in particular, appeared to be relevant both to obesity and, broadly, to brain or neural development." (PMID 27088090, 2016). "To address the possible involvement of VGF peptides in obesity and diabetes, we studied type 2 diabetes (T2D) and obese patients, and high-fat diet induced obese mice." (PMID 26562304, 2015). "To address the potential role of VGF in obesity and T2D, we studied a mouse model of high-fat diet induced obesity, in parallel with human newly diagnosed diabetics and age-matched euglycemic controls, classified according to their body mass index (BMI)." (PMID 26562304, 2015). "VGF KO mice are lean and hyper metabolic, show increased energy consumption, and are resistant to several forms of obesity, hyperglycemia and hyperinsulinemia." (PMID 22808091, 2012). "VGF gene expression was lower in obese patients, indicating that VGF may be significantly correlated with obesity; It has been reported that VGF is associated with energy balance and glucose homeostasis." (PMID 34035992, 2021). "Interestingly, ablation of the VGF gene blocked the development of obesity in diet- and gold-thioglucose mice and VGF-/- mice crossed with the (Ay/a) (agouti) mouse, whilst weight gain was attenuated in the ob/ob mouse." (PMID 28235047, 2017). "Other endocrine and/or neuroendocrine sources are likely to contribute plasma VGF peptides, including at least adrenal gland, pituitary and ovary, though possible changes in VGF peptide profiles upon obesity and/or diabetes in such locations are as yet undetermined." (PMID 26562304, 2015). "Although VGF knockout mice are smaller and thinner compared to their wild type littermates, TLPQ-21 was shown to induce anorexic effects, to activate lipolysis and modulate inflammatory pain, and to blunt obesity induced by diet." (PMID 28280458, 2017). "Hence, the various VGF peptide immunoreactivities we studied appeared to be downregulated with obesity, as well as in T2D human subjects with or without obesity." (PMID 26562304, 2015).
Cognitive impairment (10 papers, 2018 to 2025). Abnormal cognition is characterized by deficits in thinking, reasoning, or remembering. "On the other side, the decrease of CSF levels of proteins reflecting synaptic pathway integrity, such as neuronal pentraxins, VGF, and neuroserpin, was associated with cognitive impairment in neurodegenerative diseases." (PMID 39708160, 2024). "In human AD brain and cerebrospinal fluid (CSF), VGF and CHGA neuropeptides are downregulated and upregulated, respectively, compared to control brains; moreover, reduced VGF neuropeptides correlate with cognitive impairment." (PMID 41409785, 2025). "A prospective study demonstrated reduced VGF levels in CSF from patients with mild cognitive impairment, but only in those who progress to clinical AD." (PMID 31924226, 2020). "Proteins that could distinguish cognitive impairment were mainly neuronal proteins (VGF, NPTX2, NPTXR, and SCG2)." (PMID 37160957, 2023). "Interestingly, reduced VGF levels were detected prospectively in CSF from patients with mild cognitive impairment, selectively in those who develop AD20,22." (PMID 32770063, 2020). "Conversely, the downregulation of genes like NPY, CSPG5, VGF, ADAMTS2 and GPC2 among others, in astrocytes and other cell-types points to impaired neuroprotective mechanisms and compromised synaptic function contributing to cognitive deficits." (PMID 41282152, 2025). "The protein levels of VGF in cerebrospinal fluid are decreased in patients with AD compared to individuals with mild or no cognitive impairment." (PMID 30349450, 2018). "Based on experimental evidence, low levels of neuroactive peptides, such as VGF and BDNF, may contribute to memory and cognitive impairments, whereas decreased levels of CysC and the prohormone convertase-binding proteins 7B2 and proSAAS could promote amyloidogenesis." (PMID 34565482, 2021).
schizophrenia (10 papers, 2007 to 2025). A major psychotic disorder characterized by abnormalities in the perception or expression of reality. "One of the top ranking neuron-specific schizophrenia-associated hypoacetylated peaks when controlling for both scores and proportions was located ∼1.4 kb downstream of VGF, which has been reported to have differential expression in schizophrenia patients." (PMID 40300607, 2025). "In particular, the available information regarding VGF peptides and schizophrenia is limited to the human hypothalamus/CSF and restricted to the VGF N-terminal fragment with pending information coming from animal models and other VGF fragments." (PMID 28626390, 2017). "The VGF fragments to be studied were chosen for their previous involvement in schizophrenia (N-terminus), other neuronal conditions (GGGE and C-terminus) or hypothalamic mechanisms (NERPs and TLQP) that are also altered in many psychiatric diseases." (PMID 28626390, 2017). "Among the VGF peptides, those containing the N-terminus portion were altered in the cerebro-spinal fluid (CSF) and hypothalamus of schizophrenia patients." (PMID 28626390, 2017). "Our results show that PCP treatment, which causes behavioral changes that closely mimic schizophrenia, estimated by us as a disruption of PPI in PCP-treated rats, induces also changes of VGF peptide levels in the prefrontal cortex and nucleus accumbens." (PMID 28626390, 2017). "VGF overexpression has been observed in patients with schizophrenia and depression." (PMID 28680036, 2017). "Future studies are needed to uncertain the VGF peptide roles in schizophrenia." (PMID 28626390, 2017). "Abnormality of the sociality in VGF-overexpressing mice was characterized by a reduction in social behavior compared WT mice in social interaction test, which is the common symptom of model mice of schizophrenia and depression." (PMID 28680036, 2017). "“Hence, we aimed to better investigate the involvement of the VGF peptides in schizophrenia by studying their localization in the brain regions relevant for the disease, and revealing their possible modulations in response to certain neuronal alterations occurring in schizophrenia”." (PMID 28626390, 2017). "The observation of an increase of the VGF peptide in CSF from schizophrenia patients, therefore, may point to a hypometabolic state in the schizophrenia brain." (PMID 17712404, 2007). "Indeed, our previous study showed that VGF protein expression was increased in half of the investigated schizophrenia post-mortem brains." (PMID 17712404, 2007). "Therefore, we aimed to better investigate the involvement of the VGF peptides in schizophrenia by studying their localization in specific brain regions, crucial for the disease, and revealing their possible modulations in response to certain neuron alterations occurring in schizophrenia." (PMID 28626390, 2017). "Interestingly, we found that VGF peptides containing the N-terminus portion are decreased after PCP treatment in the nucleus accumbens, where we identified by MS analysis, the same N-terminal fragment (VGF24–60) previously found increased in the CSF from schizophrenia patients." (PMID 28626390, 2017).
cognitive decline (9 papers, 2018 to 2025). "Association of VGF fragments with cognitive decline was not limited to a particular neuropeptide or a region of the VGF sequence." (PMID 40334744, 2025). "The importance of VGF for AD pathology is supported by the findings that VGF partially mediates the effect of AD polygenic risk score on cognitive decline, with an effect size comparable only to beta-amyloid and tau." (PMID 40082954, 2025). "A recent study established a link between higher VGF expression in neurons and slower cognitive decline and lower odds of neurodegenerative pathologies in older adults." (PMID 40082954, 2025). "Analyses of human clinical testing and prototypic peptides show that higher levels of synaptic plasticity-related proteins, such SNAP25, SYT12, and VGF, and mitochondrial proteins, such as NDUFA, are associated with slower cognitive decline." (PMID 37338529, 2023). "At least four factors, mainly hippocampal sclerosis, VGF, and tau-tangles, were necessary to fully explain the genetic effect on cognitive decline, suggesting AD-PRS has pleiotropic effects on multiple molecular pathways." (PMID 30349450, 2018). "However, even in this case, there is no regional dependence of VGF association with cognitive decline." (PMID 40334744, 2025). "We observed stronger effects in beta-amyloid, tau-tangles and VGF, which explained approximately 30% of AD-PRS effect on global cognitive decline." (PMID 30349450, 2018). "Our findings suggest that VGF likely act through mechanisms independent of β-amyloid plaques and neurofibrillary tangles in contributing to cognitive decline." (PMID 30962425, 2019). "Therefore, the downregulation of VGF, NEUROD6, KCNF1, KCNE5, CRH, and RPH3A may contribute to the cognitive decline observed in elderly individuals with AD." (PMID 39834440, 2025).
Parkinson disease (9 papers, 2019 to 2025). A progressive degenerative disorder of the central nervous system characterized by loss of dopamine producing neurons in the substantia nigra and the presence of Lewy bodies in the substantia nigra and locus coeruleus. "Previous research revealed a reduction in the VGF immunoreactivity within the substantia nigra (SN) of rats with a 60–90% dopaminergic neuron loss and in the plasma of newly diagnosed Parkinson’s disease (PD) patients." (PMID 41166007, 2025). "For example, TLQP-21 modulates microglial function, TLQP-62 reduces Aβ plaque burden and disease-associated microglial activation, and other VGF peptides have been noted as decreasing in abundance in the brain, CSF, or blood plasma in AD or Parkinson's diseases." (PMID 40334744, 2025). "Ashwagandha; SH-SY5Y; 6-Hydroxydopamine; Parkinson's disease; Neuroprotection; Peroxidase activity; Thioltransferase activity; Peroxiredoxin; Vimentin; VGF; Protein glutathionylation." (PMID 34765761, 2021). "These terms include VGF (a.k.a. neuroendocrine regulatory peptide 1), which is selectively expressed in some neurons and shown to be reduced in AD and Parkinson’s disease." (PMID 32660529, 2020). "To determine the role of KSM-66 in neuroprotection, we studied possible changes in peroxiredoxin I, VGF and vimentin expression by analyzing lysates of 6-OHDA treated SH-SY5Y cells as a model of Parkinson with pre/post treatment with 0.5 mg/ml KSM-66 for 24 h." (PMID 34765761, 2021). "Clinical and preclinical studies link VGF-derived peptides to other neurodegenerative diseases including amyotrophic lateral sclerosis (ALS), frontotemporal dementia (FTD), Parkinson’s disease (PD) and AD." (PMID 31547145, 2019).
lung carcinoma (8 papers, 2017 to 2025). "In recent years, VGF has been found to promote tumor metastasis and poor prognosis in breast and lung cancer." (PMID 40313932, 2025). "A study indicated that VGF significantly promotes the resistance of human lung cancer cells to EGFR kinase inhibitors and is also related to the poor survival of patients with LUAD." (PMID 34635074, 2021). "VGF facilitates resistance to tyrosine kinase inhibitors in lung cancer." (PMID 35681785, 2022). "VGF has a role in energy balance and metabolism, is produced by endocrine cells of the pancreas and is known to be involved in tumorigenesis in breast cancer, lung cancer and neuroendocrine cells." (PMID 32884006, 2020). "VGF has been reported to facilitate radioresistance in DU145 and LNCaP cells as well as resistance to tyrosine kinase inhibitors in lung cancer." (PMID 33498739, 2021).
breast carcinoma (7 papers, 2013 to 2025). "Evidence that VGF gene is over-expressed in a significant number of primary breast cancers was obtained by both PCR and gene array procedures." (PMID 24277232, 2014). "Over-expression of one or more NE marker (CHGA and/or SYP and/or VGF) characterizes a significant fraction (approximately 10 %) of infiltrative breast cancers." (PMID 24277232, 2014). "As an additional result, we demonstrated that VGF a recently described NE marker showing similarities with members of the secretogranin/chromogranin family is also expressed in NE breast cancers producing CHGA and/or SYP." (PMID 24277232, 2014). "VGF gene expression by RT-PCR and gene array analysis was found in all four NE breast carcinomas that were CHGA and/or SYP positive at the mRNA and protein level." (PMID 24277232, 2014). "In addition, while genetic analyses specifically focused on NE breast tumours allowed to include them among the “Luminal A” or, less frequently, the “Luminal B” subgroup, the gene expression profile of most VGF-positive breast cancer classified them as basal." (PMID 24277232, 2014). "In addition, expression of VGF gene was detected in a significant number (10 %) of breast cancers in a large series of aggressive breast carcinomas from a published series." (PMID 24277232, 2014). "VGF is markedly upregulated in tumors such as ACC (Adrenocortical Carcinoma), BLCA (Bladder Urothelial Carcinoma), BRCA (Breast Cancer), and others." (PMID 40313932, 2025). "In breast cancer, luteolin suppresses the expression of cancer-promoting proteins (p-Akt, p-STAT3, and p-EGFR), reduces progestin-dependent VGF secretion and cell growth viability, and increases Bax expression." (PMID 40487864, 2025). "Although biological relevance data is not available for methylation of PGP9.5 and VGF in OC, our findings of methylation based good prognosis markers are supported by a recent study that reported PH of potential TSG FBXW7/hCDC4-β being related to favorable prognosis of primary breast cancer." (PMID 24086249, 2013).
frontotemporal dementia (6 papers, 2011 to 2025). Frontotemporal dementia (FTD) comprises a group of neurodegenerative disorders, characterized by progressive changes in behavior, executive dysfunction and language impairment, as a result of degeneration of the medial prefrontal and frontoinsular cortices. "In support of this hypothesis, reduction of VGF peptides in CSF and brain has been reported in different neurodegenerative conditions, including AD and frontotemporal dementia (FTD)." (PMID 40082954, 2025). "Furthermore, the connection of secretory proteins with neurodegeneration, but not with amyloid plaque pathology, is consistent with recent proteomic studies in non-AD neurodegenerative diseases, such as frontotemporal dementia, where a decline of CgA, VGF and CysC occurs in the CSF of patients." (PMID 34565482, 2021).
glioblastoma (6 papers, 2019 to 2024). The most malignant astrocytic tumor (WHO grade IV). "This includes VGF, which is linked to promoting growth and survival in glioblastoma and MDK, which is highly expressed in malignant tumours and has been shown to play a role in chemoresistance." (PMID 39540879, 2024). "Additionally, the survival of glioblastoma cells and tumour formation are linked to VGF expression in glioblastoma stem cells." (PMID 37624511, 2023). "However, the increased levels of VGF observed in both ALKAL2‐ and ALK‐F1178S‐driven NB are of interest given a recent report that VGF expression in glioblastoma promotes tumour survival and growth." (PMID 33411331, 2021). "In addition, VGF has been shown to be preferentially expressed in glioblastoma stem cells promoting glioblastoma stem cell survival and stemness and to further support survival of differentiated glioblastoma cells to promote tumor growth." (PMID 31682594, 2019).
neuroblastoma (5 papers, 2016 to 2024). Neuroblastoma (NB) is the most common solid, extracranial childhood tumor. "In particular, VGF is abundantly expressed in neuroblastoma cells and recently we found that its expression in SH-SY5Y cells is regulated by DISC1, a protein encoded by a gene that has been associated to mental disease." (PMID 28934328, 2017). "Moreover, the mass spectrometry, revealed also two further peptides: the AQEE-13 a short peptide overlapping the N-terminus region of the AQEE-30 revealed by gel chromatography in the mouse plasma, while the ELQE-20 is a VGF peptide recently identified in neuroblastoma cells." (PMID 27737014, 2016). "VGF is known to be induced by neurotrophic factors (e.g. BDNF and NGF) and also shows up-regulation after RET activation in neuroblastoma cells." (PMID 35012575, 2022). "Using the human neuroblastoma SH-SY5Y cell line, we have demonstrated that RA and NGF increase both endogenous VGF mRNA expression and VGF promoter activity." (PMID 26643910, 2016). "Using the human neuroblastoma SH-SY5Y cell line, we demonstrate that RA increases endogenous VGF expression (P<0.05) and VGF promoter activity (P<0.0001)." (PMID 26643910, 2016). "We reasoned that the neuroblastoma cell line SH-SY5Y would be a good model to study receptors and downstream mechanisms of VGF-derived peptides, given the substantial expression and secrete levels of VGF and VGF-derived peptides." (PMID 28934328, 2017).
pheochromocytoma (4 papers, 2014 to 2023). "VGF is a neuroendocrine factor, which was first discovered in a pheochromocytoma cell line when exposed to nerve growth factor (NGF)." (PMID 37624511, 2023). "VGF was originally identified in a pheochromocytoma cell line in response to the addition of the nerve growth factor (NGF)." (PMID 31682594, 2019). "The vgf (non acronymic) is a neutrophin-induced gene encoding for a primary product, VGF precursor or pro-VGF, composed of 617/615 amino acids (rat/mouse and human respectively) discovered because of a selective up-regulation by NGF in the rat pheochromocytoma cells." (PMID 28626390, 2017). "The analysis of two non-neoplastic breast specimens gave negative results, whereas two cases of pheochromocytoma expressed by RT-PCR high levels of mRNA for both CHGA and VGF, confirming VGF as a marker of NE differentiation." (PMID 24277232, 2014).
Anxiety (3 papers, 2017 to 2024). Intense feelings of nervousness, tension, or panic often arise in response to interpersonal stresses. "In addition to hyperactivity, VGF-overexpressing mice spent more time in the center of the open field than WT mice, indicating that VGF-overexpressing mice exhibit less anxiety, although the hyperactivity of VGF-overexpressing mice may affect the score." (PMID 28680036, 2017).
diabetes (3 papers, 2012 to 2015). "We examined the co-localization of VGF with both NPY and α-MSH in the human ARC and examined possible differences between controls and diabetics." (PMID 22808091, 2012). "The wide distribution of VGF in the brain, the large number of vgf-inducing factors, the complexity of the vgf ko phenotype and the co-expression of vgf in neuronal populations with opposite effects on metabolism do not allow a conclusion about the involvement of VGF in diabetes." (PMID 22808091, 2012). "VGF and α-MSH did not co-localize in the immuno reactive neurons clustered in the most ventro lateral part of the ARC, neither in controls nor in diabetics." (PMID 22808091, 2012).